IL6 (interleukin 6)
Diseases named in the same sentence as IL6 in open-access papers (continued):
Sharing a sentence is not in itself a finding about the gene and the disease.
cardiovascular disease (continued). "However, the association between IL6R genotype and longevity has not been reported despite strong evidence for association of cardiovascular disease with IL-6 and sIL-6R phenotypes." (PMID 24381713, 2013). "We investigated whether IL6 and fibrinogen gene variants can affect plasma IL-6 responses to air pollution in patients with cardiovascular disease." (PMID 19750100, 2009). "CRP and IL-6 may contribute, in part, to the observed associations between chronic infections and cardiovascular diseases." (PMID 20407653, 2009). "IL-6 is a multifunctional cytokine that has been widely implicated in cardiovascular disease." (PMID 19936194, 2008). "IL6, conventionally seen as a pro-inflammatory cytokine, was positively associated with risk factors for cardiovascular disease, e.g., BMI, eGFRcreatinine, remnants, triglycerides, and weight, but not with increasing age, which in a previous study has been associated with elevated levels of IL6." (PMID 40869066, 2025). "Moreover, there were also study reported that platelet derived levels of CRP and IL-6 were associated with IFIT1 which may involve in cardiovascular disease risk factors." (PMID 38321374, 2024). "Thus, intervention with IL-6 inhibitors could potentially reduce the risk of cardiovascular disease in patients with CHIP." (PMID 37209535, 2023). "The increased risk of cardiovascular disease associated with the presence of clonal hematopoiesis of indeterminate potential, a potent, common, age-related, independent, and newly recognized risk factor, is abrogated in patients with a loss of function mutation in IL6." (PMID 37046189, 2023). "Moreover, increases in the arterial blood pressure, circulating triglycerides (TG), and interleukin-6 (IL-6)—an inflammatory cytokine—have been observed, which may contribute to a pro-inflammatory state and increase the risk of cardiovascular disease." (PMID 36788619, 2023). "In addition to the primary findings of CANTOS where IL-1β repression resulted in a reduction in cardiovascular morbidity and mortality, residual inflammation after treatment with canakinumab (assessed through IL-6 and IL-18 tertiles) also associated with incident cardiovascular diseases." (PMID 35911546, 2022). "However, prolonged exposure to IL-6 may lead to activation of apoptosis, cell death and lower the threshold for liver injury Recent studies have shown that high serum IL-6 levels increase the risk of cardiovascular disease (CVD) and major coronary events." (PMID 22514624, 2012). "Thus, it may be concluded from the present study that C-reactive protein and IL-6 have potential utility as risk markers for cardiovascular disease in the study population." (PMID 20407653, 2009). "Of the myriad hepatic proteins that IL-6 induces with cardiovascular activities, it is increasingly clear that IL-6 is a major modulator of the coagulation pathway, where its actions shift hemostatic balance to prothrombosis, thereby increasing the risk of cardiovascular diseases." (PMID 19936194, 2008). "Further downstream C-Reactive-Protein (CRP), produced in the liver as a response to IL-6, has been demonstrated to be a sustainable clinical marker of cardiovascular disease." (PMID 41543641, 2026). "IL-6 plays a major role in the pathogenesis of cardiovascular disease interacting with aging- and metabolic-driven inflammation, two conditions with overlapping molecular mechanisms." (PMID 41543641, 2026). "Firefighters have been found to have elevated levels of inflammatory markers, including interleukin-6 (IL-6) and C-reactive protein (CRP), which are associated with an increased risk of metabolic and cardiovascular disorders." (PMID 40407432, 2025). "Studies conducted in cohorts whose primary goal is to avoid cardiovascular disease have discovered a distinct relationship between blood levels of CRP and IL-6 and the risk of developing CVD." (PMID 39844544, 2025).
cardiovascular disease (continued). "Advanced age and cardiovascular disease significantly increased IL-6 and TNF-α levels while reducing IgG levels." (PMID 40137715, 2025). "Other anti-inflammatory agents like colchicine reduce IL-6 indirectly and are used off-label in cardiovascular disease." (PMID 41511355, 2025). "The survival analysis revealed significantly reduced survival times in patients with advanced age, cardiovascular disease, or high IL-6 levels." (PMID 40137715, 2025). "The expanding literature has led to understanding of the proatherogenic role for IL-6 in cardiovascular disease and thus the potential for IL-6 inhibition as a novel method for vascular protection." (PMID 39858645, 2025). "Previous studies have attempted to therapeutically target proteins such as IL-6 and P-Selectin in other cardiovascular diseases with little result." (PMID 40278353, 2025). "Reduced levels of ADP are strongly associated with cardiovascular disease in animal models, with increased expression of anti-inflammatory genes, and suppression of pro-inflammatory gene expression (TNF α and IL-6)." (PMID 40137085, 2025). "By reducing inflammatory cytokines such as IL-6 and TNF-α, SCC addresses a key driver of metabolic and cardiovascular diseases associated with air pollution exposure." (PMID 40005045, 2025). "IL-6, in contrast, occupies a more central position in the inflammatory cascade and is a key factor in the pathophysiology of cardiovascular diseases." (PMID 40870513, 2025). "A possible explanation lies in the fact that regular PA stimulates the release of myokines, which regulate inflammatory markers such as TNF-α, IL-6, IL-1β, and CRP, all of which are associated with cardiovascular disease." (PMID 40868631, 2025). "In another meta-analysis of advanced biomarkers in cardiovascular disease (CVD) among asymptomatic adults, hs-CRP and NT-proBNP predicted incident events but IL-6 was observed to have stronger associations in certain settings." (PMID 41375916, 2025). "All these results support the significant role that IL-6 plays in the pathophysiology of cardiovascular disease in RA patients." (PMID 41010664, 2025). "The increased concentrations of preoperative hs-cTnT, NT-proBNP, and GDF-15 in patients with high preoperative IL-6 suggest the presence of subclinical cardiovascular disease." (PMID 40491666, 2025). "The SMART study found that higher levels of IL-6, CRP, and D-dimer are associated with an increased risk of cardiovascular diseases in PWH, as an independent factor." (PMID 39456715, 2024). "While steroids are associated with the development of cardiovascular disease, anti-rheumatic drugs like methotrexate, tumor necrosis factor (TNF) inhibitors, and IL-6 inhibitors have been reported to mitigate this risk." (PMID 39165751, 2024). "Patients with DM + COPD and cardiovascular disease exhibit moderate IL-6 levels at 71.0 pg/mL and 66.0 pg/mL, respectively." (PMID 39469275, 2024). "Cytokines from the interleukin-6 (IL6) family have emerged as key players and potential predictors of cardiovascular disease onset and prognosis." (PMID 39596280, 2024). "This systematic review aims to evaluate the current evidence on the roles of IL-6 and IL-1β in cardiovascular diseases." (PMID 39057626, 2024). "Future research should focus on further elucidating the mechanistic pathways through which IL-6 and IL-1β contribute to cardiovascular disease progression." (PMID 39057626, 2024). "The radar chart shows that patients with DM + HTN + cardiovascular disease have the highest IL-6 levels (119.3 pg/mL), followed by patients with DM + HTN (98.6 pg/mL) and HTN + cardiovascular disease (91.4 pg/mL)." (PMID 39469275, 2024). "In cardiovascular disease, IL-6 is synthesized by various cell types such as macrophages, monocytes, endothelial cells, vascular smooth muscle cells, and fibroblasts." (PMID 39202593, 2024).
cardiovascular disease (continued). "In a similar way, IL-6, one of the most studied cytokines in cardiovascular inflammation, is increased in cardiovascular diseases." (PMID 39328992, 2024). "In fact, IL-6 inhibition, supported by MR evidence, is being developed as a treatment for cardiovascular disease." (PMID 38951047, 2024). "Logistics regression models were applied to determine the association between ACS development and IL-6, age, D-dimer, CRP, and concurrent cardiovascular disease (CVD), as common ACS-related risk factors." (PMID 39395941, 2024). "The meta-analysis conducted in this review further supports the role of IL-6 as a critical biomarker for cardiovascular disease progression." (PMID 39057626, 2024). "PCA sulfate lower the production of interleukin-6 (IL-6) and vascular cell adhesion molecule-1 (VCAM-1), pro-inflammatory cytokine genes that are linked to cardiovascular diseases." (PMID 38958528, 2024). "In the green cluster, mendelian randomization was employed to examine the role of the IL-6 signaling pathway in cardiovascular disease." (PMID 38579070, 2024). "Our review highlights the significant roles of IL-6 and IL-1β in the pathogenesis and progression of cardiovascular diseases." (PMID 39057626, 2024). "Circulating interleukin-6 (IL-6) as a biomarker for systemic low-grade inflammation concerning environmental factors/determinants and cardiovascular diseases in prior twin studies." (PMID 38397668, 2024). "Especially patients with DM-2, but also those with CKD as well as cardiovascular disease, experience an increase in IL-6 levels due to low-grade inflammation." (PMID 38448675, 2024). "In the further analysis on the association between VTE-associated proteins and cardiovascular comorbidities, genetically predicted levels of interleukin-6 receptor subunit alpha (IL-6 sRa) were inversely associated with VTE and 4 cardiovascular diseases." (PMID 38029854, 2024). "Research has demonstrated that measuring IL-6 levels in plasma can provide an indicator of the presence of cardiovascular disease." (PMID 39065817, 2024). "As drugs targeting IL-1β and IL-6 are available for use in cardiovascular disease treatment, further investigation of these interleukins in the disease manifestation and progression in adult human tissue and human disease models is critical." (PMID 38776872, 2024). "The findings in this study are important as they increase interest in research on measuring IL-6 in SLD and understanding the high economic and health burden and underlying cardiovascular disease risk associated with its diagnosis." (PMID 39766906, 2024). "The cytokine interleukin-6 (IL-6) plays a central role in the inflammation cascade as well as cardiovascular disease progression." (PMID 39015379, 2024). "Studies have shown that inflammation markers such as high-sensitivity C-reactive protein (hs-CRP) and interleukin-6 (IL-6) are elevated in patients with cardiovascular disease." (PMID 37048603, 2023). "The proinflammatory cytokine interleukin 6 (IL-6) is a essential marker of innate immunity that is considered to play an important proatherogenic role for cardiovascular disease." (PMID 38067150, 2023). "Tissue sodium accumulation was shown to be correlated with plasma IL-6 levels in HD patients with cardiovascular disease progression." (PMID 37176037, 2023). "The aim of this study was to assess the association between fibrinogen (FIB), interleukin-6 (IL-6), C-reactive protein (CRP) and galectin-3 (Gal-3) and the risk of cardiovascular disease using meta-analysis." (PMID 37485268, 2023). "Tissue sodium accumulation in HD patients with cardiovascular disease progressed in parallel with higher plasma concentrations of the inflammatory marker IL-6." (PMID 37176037, 2023). "It was reported that inflammatory markers such as IL-6 levels significantly predict macrovascular complications and mortality in patients with T2DM who have baseline cardiovascular disease or risk factors." (PMID 36839255, 2023).
cardiovascular disease (continued). "Cytokines such as IL-1, IL-6, IL-10, and TNF-alpha also play a major role in the inflammatory processes underlying cardiovascular disease." (PMID 37509542, 2023). "So, the roles of TNF-α and IL-6 in VSMCs are complex, and their implications for cardiovascular diseases are significant." (PMID 37873791, 2023). "IL-6 levels were higher among women with cardiovascular disease related pregnancy complications (hypertensive disorder of pregnancy, preterm birth, and small for gestational age baby) 3 and 9 months postpartum." (PMID 37887854, 2023). "Inflammation and cardiovascular disease are associated with expressions of ANP, cTnT, NOS3, MMP-9, and IL-6 genes." (PMID 38348351, 2023). "Pro-inflammatory cytokines such as tumor necrosis factor alpha and interleukin-6, involved in the pathogenesis of RA, are also independently predictive of subsequent cardiovascular disease (CVD)." (PMID 36983855, 2023). "Interleukin 6 (IL-6) signaling plays a crucial role in propagating downstream inflammation cascades, making it an attractive target for cardiovascular diseases." (PMID 38049831, 2023). "Since inflammation plays a crucial role in cardiovascular diseases, we further utilized ELISA to measure the levels of IL-6, IL-1β, and TNF-α in the supernatant of cells after cGAS knockdown." (PMID 38124089, 2023). "IL-6 is an important inflammatory factor with pleiotropic effects in different tissues and plays divergent roles in cardiovascular diseases." (PMID 37018396, 2023). "The interaction between IL-6 and AngII can create a positive feedback loop that amplifies inflammation and exacerbates the pathophysiology of certain diseases, including cardiovascular diseases, where both IL-6 and AngII play significant roles." (PMID 38137381, 2023). "Assessed by its role in cardiovascular disease, IL-6 canbe a good biomarker in determining cardiovascular disease risk." (PMID 39077574, 2023). "There is growing evidence that IL-6 and TNF have significant inhibitory effects on myocardial metabolic processes in both ventricles, which can worsen the course of cardiovascular disease and increase the risk of tachyarrhythmia." (PMID 36059969, 2022). "Another large study of 1,293 non-disabled elderly people found that higher levels of circulating IL-6 and CRP were associated with all-cause mortality and specifically, cardiovascular disease." (PMID 35821823, 2022). "IL-6 is a marker of progressive AS, which can induce or aggravate cardiovascular disease by promoting plaque growth and is an independent predictor of plaque progression." (PMID 35811610, 2022). "Recent pathophysiological progress in the understanding of IL-6 signaling and the development of selective anti-IL-6 therapeutics in cardiovascular disease are being considered to prevent the progression of CAD." (PMID 36014939, 2022). "In our study, the higher levels of TNF-α, IL-1β, and IL-6 in PBMCs from AP individuals were also accompanied by the upregulation of several cardiovascular disease biomarkers like adiponectin and angiogenin." (PMID 35300329, 2022). "In general, inflammatory indicators like IL-6 produce cardiovascular remodeling and arterial resistance and increase the incidence of cardiovascular disease (CVD)." (PMID 36465453, 2022). "Due to reported links to IL-6, inflammation, cardiovascular diseases, and/or toxicology, we selected the following four lncRNAs: CDR1as, CoroMarker, LINC00460, and MALAT-1 as potential biomarkers for the effects of Zn/Cu particles." (PMID 35915466, 2022). "In one study, ZnO NPs decreased cell viability and increased levels of 8-hydroxy-2’-deoxyguanosine (8-OHdG), interleukin (IL)-6, nitric oxide (NO), and downregulated cardiovascular disease-related genes in human coronary artery endothelial cells (HCAECs)." (PMID 36361726, 2022). "The volume of visceral adipose tissue correlates, among other things, with mortality due to cardiovascular diseases or high serum levels of interleukin 6 (IL-6)." (PMID 36233489, 2022).
cardiovascular disease (continued). "More information is needed in the literature about haplotypic data of IL6 and its relationship with cardiovascular disease." (PMID 36337884, 2022). "IL-6 possesses a number of features that contribute to the development of cardiovascular disease, as well as a beneficial influence on lipid processing." (PMID 36171973, 2022). "These lipopolysaccharides, after interaction with toll-like receptors, trigger pro-inflammatory responses related to cardiovascular disease, such as interleukin-6." (PMID 35837017, 2022). "Simultaneously, leptin can stimulate inflammatory responses and up-regulate pro-inflammatory elements such as TNF- and IL-6, hastening the onset and progression of cardiovascular disease." (PMID 36186974, 2022). "AF can stimulate the release of pro-inflammatory cytokines and chemokines related to cardiovascular disease and tissue injuries such as angiotensin II, interleukin (IL)-6, IL-8, and tumor necrosis factor (TNF)-α." (PMID 34781940, 2021). "Nonetheless, the pro-inflammatory cytokines such as TNF-α and IL-6, are responsible for the development and progression of cardiovascular diseases." (PMID 34073506, 2021). "In Cardiovascular Diseases, some researchers found that the level of IL-6 in myocardial tissue from MI rats increased greatly." (PMID 34504432, 2021). "More notably, the serum of cardiovascular disease patients contains a large quantity of inflammatory mediators, including interleukin-6 (IL-6), interleukin-1β (IL-1β), C-reactive protein, and tumor necrosis factor-α (TNF-α)." (PMID 34830730, 2021). "The inflammatory response of cortisol is congruent to the fact that cardiovascular diseases are often related with proinflammatory cytokines such as IL-1, IL-6, and TNF-α." (PMID 33466883, 2021). "IL-6 is a recognized inflammatory marker and has been utilized to represent chronic inflammation leading to cardiovascular disease." (PMID 34644368, 2021). "Lastly, the proteomic content of plasma EVs isolated from HIV-infected individuals with T2D, was at top related to metabolic and cardiovascular disease genes and upstream regulation of inflammatory pathways, including IL-6 and inflammasome activation (IL-1β)." (PMID 34754007, 2021). "Increasing plasma levels of IL6 was correlated to increasing plasma levels of ceramide in patients with cardiovascular disease." (PMID 34638448, 2021). "A large number of studies have shown that the level of IL-6 is closely related to the occurrence of cardiovascular diseases and plays an important role in endothelium dysfunction." (PMID 33171330, 2021). "It seems that the role of AAG in inflammatory progression needs to be further investigated, also in view of the recent data that demonstrated the importance of IL-6 and IL-6R (interleukin-6 receptor) in cardiovascular diseases." (PMID 34566895, 2021). "Intercellular IL-6 is an inflammatory cytokine, which plays an important role in inflammation and immune response and is closely related to cardiovascular diseases." (PMID 32677975, 2020). "In overweight adults, CP correlates with neutrophil blood count and cardiovascular disease, and with other inflammatory molecules such as IL6 or C reactive protein (CRP)." (PMID 32245056, 2020). "IL-6, a pro-inflammatory cytokine, has been observed to play roles in a variety of human and mouse cardiovascular diseases." (PMID 33099539, 2020). "Kidney 4, which is from a donor with a history of significant cardiovascular disease, had the most severe acute tubular injury, the highest levels of thrombomodulin and IL-6, and the greatest downregulation of miR-126-3p." (PMID 33305131, 2020). "Although IL-6 has been reported to exhibit both pro- and anti-inflammatory properties, there is also information indicating that this cytokine can protect against cardiovascular diseases." (PMID 32824277, 2020).